PPARG (peroxisome proliferator activated receptor gamma)
Diseases named in the same sentence as PPARG in open-access papers (continued):
Sharing a sentence is not in itself a finding about the gene and the disease.
colon carcinoma (continued). "Since 15-deoxy PGJ2 is the natural ligand of PPARγ, we next determined the effect of these PUFAs on PPARγ in experimentally induced colon cancer." (PMID 24999478, 2014). "Incubation with pioglitazone or telmisartan only significantly downregulated relative PPARγ mRNA expression in all three colon cancer cell lines, while upregulating CSTA in an evidently dose-dependent manner." (PMID 25360175, 2014). "The antiproliferative and apoptotic effects of telmisartan in the human colon cancer cells were significant at therapeutic serum concentrations, and telmisartan exhibited a potency at least equivalent to the full PPARγ agonist, pioglitazone." (PMID 25360175, 2014). "The PPARγ gene is expressed in many tissues, including high levels of expression in normal colonic mucosa, colorectal adenocarcinomas, and colon cancer cell lines." (PMID 23476786, 2013). "It has also been demonstrated that PPARγ is a nuclear receptor of prostaglandins and leukotrienes as well, and it down-regulate cell proliferation in colon cancer cells." (PMID 23451083, 2013). "Although PPARγ is expressed at significant levels in human colon cancer cells and tissues, the role of PPARγ activation in colon cancer is still controversial." (PMID 23476786, 2013). "Our recent reports suggest that endogenous LPA agonist, cPA, which is a bona fide second messenger and a physiological inhibitor of PPARγ has emerged as a potential therapeutic target in the treatment of colon cancer." (PMID 23476786, 2013). "PPARγ agonists induce apoptosis particularly in colon cancer cells and have inhibitory effects on cell proliferation." (PMID 23451083, 2013). "In this study, our results showed that PPARγ mRNA and protein were expressed at various levels in 4 colon cancer cell lines." (PMID 23516550, 2013). "Although PPARγ is expressed at significant levels in human colon cancer cells and tissue, the role of PPARγ activation in colon cancer is still controversial." (PMID 23516550, 2013). "Some reports indicate that PPARγ is expressed at considerable levels in human colon cancer cells and tissues and that treatment with PPARγ agonists and antagonists reduces the cell growth rate." (PMID 23476786, 2013). "To this end, we searched for proteins that interact with peroxisome proliferator-activated receptor gamma (PPARγ), which is expressed at significant levels in human colon cancer cells and tissues." (PMID 24288667, 2013). "To date, a limited number of direct targets for PPARγ have been identified in studies using colon cancer cells." (PMID 23516550, 2013). "Despite this observation, the number of studies investigating PPARγ in human subjects with colon cancer is limited." (PMID 22761953, 2012). "In mouse models of colon cancer, activation of PPARγ by the TZD troglitazone increased the frequency and size of colon tumors in both C57BL/6J-APCMin/+ mice and wild-type C57BL/6J mice." (PMID 22934105, 2012). "Thiazolidinedione, a synthetic activator of PPARγ, inhibits the growth of PPARg-expressing human colon cancer cells by inducing terminal differentiation and a marked increase in p21 abundance." (PMID 22580498, 2012). "On the other hand, inhibiting PPARγ prevents proliferation of human colon cancer HT-29 cells, as evidenced by challenge with cyclic phosphatidic acid (cPA), a structural analog of lysophosphatidic acid (LPA), and a specific, high-affinity PPARγ antagonist." (PMID 23028383, 2012). "It was shown that activation of PPARγ by troglitazone increased the frequency and the size of colon tumors in C57BL/6J-APCMin/+ mice." (PMID 23024650, 2012). "In colon cancer and non-small-cell lung carcinoma cells, PPARγ induces the expression of the transcriptional repressors TSC22 and GADD153, respectively." (PMID 22848209, 2012). "More recent studies from our laboratory have addressed the epigenetic regulation of PPARG transcription in human colon cancer." (PMID 22848209, 2012).
colon carcinoma (continued). "A direct role of PPARγ as tumor suppressor is confirmed by the observation that hemizygous Pparg colon-specific knockout mice display a significantly higher incidence of colon tumors following AOM treatment." (PMID 22848209, 2012). "Agonist-induced activation of PPARγ in a colon cancer xenograft model showed reduction of tumor growth, whereas it resulted in tumor promotion when PPARγ was activated in a genetic model of colon cancer (APCMin mice)." (PMID 21144036, 2010). "Many in vitro studies have revealed that activation of PPARγ inhibits proliferation and induces apoptosis of some colon cancer cell lines." (PMID 19884989, 2009). "For example, Curcumin, a widely recognized dietary agent with a strong ability to inhibit NF-κB and COX-2, was found to activate the PPARγ pathway in colon cancer." (PMID 19884989, 2009). "When treated with CLA,PPARγ expression is increased, and APCand c-myc proteins are downregulated in the human colon cancer cells, andfinally proliferation of cancer cells is inhibited by CLA." (PMID 18483618, 2008). "For example, mice withheterozygous germ-line deletions of Pparγ have an increased proclivity to develop N-methyl-N-nitrosourea carcinogen-induced colon cancer comparedwith wild-type mice, supporting a growth inhibitory role for Pparγ." (PMID 18528521, 2008). "Inhibitory effect of PPARγ to cancer metastasis is reported in severalcancers, such as nonsmall cell lung cancer, colon cancer, thyroid cancer, andbreast cancer." (PMID 18551182, 2008). "A tumor suppressor role forPPARγ is also supported by the inhibitory effect of PPARγ agonists on colon tumor growth, and mammary carcinogenesis." (PMID 18566686, 2008). "In humans, multiple lines of evidence support an unequivocal function for PPARγ signaling in colon cancer." (PMID 18528521, 2008). "The evidence in support of PPARγ as a colon cancer suppressor is based upon arelatively small number of observations, and not all of these observations areconsistent with each other." (PMID 18615192, 2008). "Activation of PPARγ has also been reported to inhibit tumor cell growth byupregulation of the transcriptional repressor TSC22 in colon cancer cells and GADD153 in nonsmall-cell lung carcinoma cells." (PMID 18551185, 2008). "The increased risk for colon cancer inpatients with ulcerative colitis relates to the severity and duration ofdisease; by suppressing inflammation in the colon, drugs such as thethiazolidinediones or other PPARγ agonists might play a role in colon cancerprevention." (PMID 19125177, 2008). "Therole of PPARγ as a suppressor of colon carcinogenesis inrodents is beyond question, but the evidence that PPARγ is a colon cancer suppressor in humans is notso compelling." (PMID 18615192, 2008). "Overall, existing evidence indicates that PPARγ agonists have a potentialto inhibit cancer formation in the distal colon, but they are practically inactive in advancedstages of colon cancer." (PMID 18779870, 2008). "Thebest evidence for a tumor suppressive role of PPARγ in humans comes from studies of establishedhuman colon cancer cell lines." (PMID 18615192, 2008). "Thisobservation was consistent with the report that whole animal hemizygousknockout of PPARγ suppressed AOM-mediated colon tumor formationin mice." (PMID 18615192, 2008). "Preclinical studies of solid malignanciessuch as liposarcomas, breast, and colon cancers also provide support for the greaterefficacy of combined regimens of PPARγ and RXR ligands compared to monotherapy." (PMID 19125177, 2008). "In the study that evaluated PPARγ haploinsufficiencyin an Apc+/1638Nbackground, the investigators alsodetermined the effect of Pparγ+/− in azoxymethane-mediated colon cancer." (PMID 18784849, 2008). "The role of PPARγ inAOM-induced colon tumorigenesis was directly demonstrated by the study showingthat the incidence of colonic tumors increased in the hemizygous knockout ofPPARγ that received AOM." (PMID 18483618, 2008).
colon carcinoma (continued). "Themajor controversy in the PPARγ field has revolved around two high-profilepapers that reported increased colon tumor formation in APC+/Min mice treated with thiazolidinediones." (PMID 18615192, 2008). "Contrary to theseresults, PPARγ haploinsufficiency produced a greater rate andnumber of colon tumors following azoxymethane-induced carcinogenesis, implying that PPARγ acts as a tumor suppressor rather than as anoncogene." (PMID 18566686, 2008). "Themost compelling case for pharmacological application of PPARγ agonists in colon cancer is as a preventiveagent." (PMID 18615192, 2008). "“In vivo” PPARγ and PPARα proteins content wasevaluated in cancer specimens from patients undergoing surgery toremove colon tumors." (PMID 17389773, 2007). "PPARγ is overexpressed not only in colon cancer but alsoin other tumor types, such as in primary human lung tumors." (PMID 17389773, 2007). "With regard to the role of PPARγ in colon cancer, the available data are conflicting and mostly obtained in cell lines or in animal models." (PMID 16854216, 2006). "Activation of PPARγ by ligands such as troglitazone and 15-deoxy-Δ12,14 – prostaglandin J2 has been shown to down-regulate c-myc mRNA and protein expression in colon cancer cells and leukemic cell lines." (PMID 16405739, 2006). "In colon cancer, ligand activation of PPARγ-mediated differentiation of certain colon cancer cells results in the upregulation of tumour suppressor genes caveolin 1 and 2 and repression of cyclin D1 expression." (PMID 15583697, 2005). "The inhibitory effect of PPARγ activation on COX-2 expression is also reported in HT-29 human colon carcinoma cells." (PMID 15266333, 2004). "Furthermore, treatment with troglitazone, a peroxisome proliferator-activated receptor gamma (PPARγ) ligand, significantly diminished colon cancer growth in mice." (PMID 41373547, 2025). "On the other hand, HOXC11, an oncogene, may promote cell proliferation in colon cancer and renal clear cell carcinoma by down-regulating PPARγ signaling." (PMID 39875357, 2025). "6‐Shogaol, a major bioactive ingredient in the rhizomes of ginger, could induce PPARγ transcriptional activity to suppress NFκB activation and increase apoptosis in breast and colon cancer cells." (PMID 41019996, 2025). "The connection between PPARG and the Wnt-signaling pathway may be a possible explanation for the effect of PPARG on early stages of colon cancer carcinogenesis." (PMID 38378472, 2024). "Moreover, 15-d-PGJ-2 inhibited colitis and colon cancer in mice by suppressing NF-κB signaling via PPARγ signaling activation." (PMID 38704736, 2024). "Moreover, PGE2 has also activated the PI3K-Akt-PPARγ cascade in ApcMin/+ mice to promote colon tumor cell survival." (PMID 38704736, 2024). "Thus, while its overexpression inhibits colon cancer cell proliferation, PPARγ agonists suppress melanoma growth in mice." (PMID 37770940, 2023). "Activation of PPARγ is well known to be beneficial in the treatment of breast and colon cancers." (PMID 36620594, 2022). "Moreover, increased mRNA and protein levels of PPARγ, involved in fatty acid uptake and transport, were reported in colon cancer cells (SW 480) exposed to vitamin E." (PMID 36615330, 2022). "The macrophage-specific deletion of PPARγ abrogated pro-tumorigenic CLA effects in colon cancer." (PMID 35954274, 2022). "Similarly, linoleic acids have been reported to inhibit colon cancer metastasis through PPARγ activation." (PMID 35954274, 2022). "Some previous reports suggested PPARγ agonists inhibited colon cancer growth and liver metastasis." (PMID 33122687, 2020). "Additional findings show decreased AOM-induced colon tumors only in PPARγ−/− mice fed SM." (PMID 32260440, 2020). "Through interacting with T cell transcription factor-4 (Tcf-4) and beta-catenin, peroxisome proliferator activated receptor gamma (PPAR gamma) may determine colon cell fate and serve as a target of the Wnt pathway in colon cancer cells." (PMID 32117736, 2020).
colon carcinoma (continued). "In later papers, the inhibitory effect of PPARγ activation was shown in gastric cancer cell lines and colon cancer, and it was demonstrated that its effect was enhanced by the simultaneous addition of 9-cis RA, causing G1 cell cycle arrest and increase of annexin V-positive cells." (PMID 32012980, 2020). "In addition, PPARγ has been found to have an anti-neoplastic property as it can induce apoptosis and differentiation of colon cancer cells both in vivo and in vitro." (PMID 31540047, 2019). "Treatment of colon cancer cells with 15-hydroxy-eicosatetraenoic acid (15S-HETE), an endogenous ligand for PPARγ, arrests the growth of colon cancer cells via a PPARγ dependent pathway involving increased expression of KLF10 and decreased Bcl-2 (B cell lymphoma 2) expressions." (PMID 29799499, 2018). "The results of subsequent meta-analysis suggested that PPARG rs1801282 C>G polymorphism might be a protective factor for CRC, especially in Asians, colon cancer and rectum cancer subgroups." (PMID 29246001, 2017). "Nf-κB has been reported along with PPARγ in the colon cancer andpancreatic cancer." (PMID 28246465, 2016). "Although PPARγ is well known for its function in adipocyte gene expression, insulin sensitivity and lipogenesis, other roles for modulating the growth and differentiation of colon cancer cells have also been discovered." (PMID 26569228, 2015). "In addition, a significant reduction in tumour volume between colon tumours xenograft mice given troglitazone (a specific ligand for PPARγ) vs. those given vehicle was observed." (PMID 26569228, 2015). "Similarly as in adipocytes, PPARγ expression is also maintained at relatively high levels in numerous human colon cancer cell lines and primary colon tumours." (PMID 26492315, 2015). "The disparate results might be explained by in vitro studies in colon cancer cell lines showing that the level of PPARγ expression correlated to cells' sensitivity to proliferation inhibition." (PMID 25866814, 2015). "Therefore, in current study, ceramide, COX-2, 15-deoxy prostaglandin J2(15-deoxy PGJ2), PPARγ, and β-catenin were estimated to evaluate the effect of fish oil on lipid mediated and Wnt/β-catenin signaling in colon carcinoma." (PMID 24999478, 2014). "A marginal decrease in the expression of PPARγ in the initiation phase might be related to the early stages of colon cancer." (PMID 24999478, 2014). "However, it also activates PPARγ in colon cancer cells in vitro, inducing the suppression, differentiation, apoptosis and reversal of malignant changes." (PMID 25360175, 2014). "Therapies directed at PPARγ expression or its binding partners may lead to novel approaches to treat colon cancer." (PMID 23516550, 2013). "cPA binding to and inhibition of PPARγ might be involved in cPA-induced inhibition of colon cancer cell growth." (PMID 23476786, 2013). "PPARγ-interaction partners may provide insight into the biological functions of PPARγ and provide us with a better understanding of the events involved in colon cancer." (PMID 23516550, 2013). "In the present study, we showed that PSF interacts with PPARγ in colon cancer cells." (PMID 23516550, 2013). "Similarly, in mouse models of colon cancer, PPARγ agonists inhibited tumor growth or colon carcinogenesis." (PMID 22761953, 2012). "The role that epigenetic mechanisms play is also addressed disclosing novel crosstalks between PPARG signaling and the epigenetic machinery and suggesting how this dysregulation may contribute to colon cancer development." (PMID 22848209, 2012). "The cellular proliferation caused by PPARβ, induced by specific ligands, may lead to overexpression and inhibition of PPARγ heterodimerization, and subsequently contribution to human colon cancer development." (PMID 20182546, 2010). "The authors suggested that PPARγ might have greater impact as a preventative agent than a therapeutic agent, as in experimental studies of colon cancer." (PMID 20650001, 2010).
colon carcinoma (continued). "PPARγ-active C-DIMs inhibit growth and activate caspase-dependent apoptosis in colon cancer cells." (PMID 21129193, 2010). "PPARγ is expressed at high levels in primary colon tumors and colon cancer cell lines." (PMID 20885923, 2010). "Furthermore, PPARγ agonists are able to induce differentiation, cell cycle arrest, and apoptosis in human colon cancer cell lines." (PMID 20182546, 2010). "Although there is a contradictory study in which APCmin /+ mice showed an increased number of polyps when subjected to a PPARγ agonist, many research studies have shown that PPARγ agonists seem to have inhibitory effects on the proliferation of colon cancer cells." (PMID 20885923, 2010). "Many studies have investigated the relation between PPARγ and colon cancer." (PMID 20885923, 2010). "The inhibitory effect of PPARγ activation on colon cancer could be attributed to several mechanisms." (PMID 19884989, 2009). "The expression pattern of PPARγ in colon cancer has been previously reported." (PMID 19884989, 2009). "In contrast, another study showed that mutantPPARγ gene has not been detected in human colon tumor samples andCRC cell lines, suggesting that PPARγ mutations in human CRC is a rare event." (PMID 18551185, 2008). "Although in vitro and in vivostudies demonstrate a role for PPARγ in modulating growth and differentiation ofhuman colon cancer cell lines, thiazolidinedione treatment with rosiglitazone(BRL49653) or troglitazone stimulated rather than inhibited the development ofcolon tumors in APCmin/+ mice." (PMID 19125177, 2008). "However, in the ApcMin mouse colon tumor model, “glitazone” PPARγ agonists increased the number of colon, butnot small intestine polyps, as well as colon adenomas." (PMID 18566686, 2008). "However, many (in our experience most) human colon cancer cell lines areresistant to growth inhibition by concentrations of thiazolidinediones that aresufficient to maximally activate PPARγ." (PMID 18615192, 2008). "Moreover, the results obtained on treating cell lines with PPAR ligands confirm observations in colon cancer: there is an inverse correlation between PPARα and Bcl-2 and between PPARγ and c-Myc." (PMID 17389773, 2007). "Indeed and in contrast to PPARγ, PPARδ was found frequently overexpressed in colon cancer cells and tumors of chemically-initiated animals." (PMID 17767717, 2007). "A K422Q mutation has been described previously in exon 6 of PPARγ in colon cancer cell lines, but it did not alter ligand-induced transactivation." (PMID 16969347, 2006). "Stimulation of PPARγ has been shown to lead to apoptosis in a colon cancer cell line." (PMID 14562008, 2003). "Ligand-induced PPARγ activation has been shown to promote differentiation and to induce cell growth inhibition and apoptosis in several types of human cancer, including colon cancer, breast cancer, lung cancer, prostate cancer, gastric cancer, liposarcoma, and leukaemia." (PMID 12454768, 2002). "In many other studies PPARγ agonists induced apoptosis in bladder cancer, gastric carcinoma, lung cancer, esophageal adenocarcinoma, pancreatic cancer, hepatocellular carcinoma, neuroblastoma, melanoma, glioblastoma, leukemia, leiomyoma, mesothelioma, and colon carcinoma." (PMID 35954274, 2022). "The difficulty in categorizing PPARγ activation in cancer therapy as beneficial or disadvantageous is also well-illustrated in a study from Baron and colleagues, who investigated the effects of ciglitazone in two different colon cancer cell lines: HT29 and SW480 cells." (PMID 35954274, 2022). "High-fat diets may also lead to colon cancer formation potentially due to PPARγ activation." (PMID 35163356, 2022). "However, in human colon cancer cell lines, PPARγ inhibited tumor-cell proliferation." (PMID 35954274, 2022). "Interestingly in colon cancer there are differing older reports as to the effect of PPARγ agonists." (PMID 24672773, 2014).